ATP5MC2 (ATP synthase membrane subunit c locus 2)
Description:
Mitochondrial membrane ATP synthase (F(1)F(0) ATP synthase or Complex V) produces ATP from ADP in the presence of a proton gradient across the membrane which is generated by electron transport complexes of the respiratory chain. F-type ATPases consist of two structural domains, F(1) - containing the extramembraneous catalytic core and F(0) - containing the membrane proton channel, linked together by a central stalk and a peripheral stalk. During catalysis, ATP synthesis in the catalytic domain of F(1) is coupled via a rotary mechanism of the central stalk subunits to proton translocation. Part of the complex F(0) domain. A homomeric c-ring of probably 10 subunits is part of the complex rotary element.
Synonyms: ATP5G2; ATP5A
Tractability: Antibody: UniProt predicts a signal peptide or a membrane-spanning region. PROTAC: ubiquitination databases record sites on it.
Gene: Protein-coding gene on chromosome 12 (53,632,726 to 53,677,651, reverse strand). Ensembl gene ENSG00000135390.
Subcellular location: Mitochondrion membrane
Pathways (Reactome):
Metabolism: Formation of ATP by chemiosmotic coupling
Organelle biogenesis and maintenance: Cristae formation
Gene Ontology:
Molecular function: protein binding; proton transmembrane transporter activity
Biological process: proton motive force-driven ATP synthesis; proton transmembrane transport
Cellular component: mitochondrion; mitochondrial inner membrane; proton-transporting ATP synthase complex; mitochondrial membrane; proton-transporting two-sector ATPase complex, proton-transporting domain
Genetic constraint (gnomAD): Loss-of-function variants: 10 observed, 11.48 expected, observed/expected ratio (o/e) 0.87, 90% interval 0.54 to 1.47. The upper end of that interval is the gene's LOEUF score, 1.47, which puts it in group 6 of 6, group 1 being the genes least tolerant of losing a copy. Missense variants: 130 observed, 177.71 expected, observed/expected ratio (o/e) 0.73, 90% interval 0.63 to 0.85. Synonymous variants: 64 observed, 70.45 expected, observed/expected ratio (o/e) 0.91, 90% interval 0.74 to 1.12.
Homologues: Orthologues: mouse Atp5mc2 (91% identical), rat Atp5mc2 (90% identical), guinea pig ATP5MC2 (89% identical), pig ATP5MC2 (88% identical), rat AABR07007730.1 (87% identical), rat Atp5mc2l1 (81% identical), Caenorhabditis elegans Y82E9BR.3 (54% identical). Paralogues in human: ATP5MC3 (75% identical), ATP5MC1 (67% identical).
Diseases named in the same sentence as ATP5MC2 in open-access papers:
ATP5MC2 is named in the same sentence as 4 diseases in open-access papers, as found by Europe PMC text mining. Sharing a sentence is not in itself a finding about the gene and the disease. The quoted sentences say what the papers report.
Parkinson disease (1 paper, 2025). A progressive degenerative disorder of the central nervous system characterized by loss of dopamine producing neurons in the substantia nigra and the presence of Lewy bodies in the substantia nigra and locus coeruleus. "In contrast, the Amyg showed upregulation of genes linked to oxidative phosphorylation (Atp6v1e1, Atp5mc2, Atp6v0e2), Parkinson disease (Snca, Calm1, Slc39a10), and regulation of actin cytoskeleton (Arpc3, Nckap1, Cfl1), indicating increased mitochondrial metabolism and structural plasticity." (PMID 41394722, 2025).
cancer (1 paper, 2024). A tumor composed of atypical neoplastic, often pleomorphic cells that invade other tissues. "For malignant cells, consistently upregulated metabolic genes were predominantly associated with cancer hallmark pathways, including glycolysis (GAPDH, GPI and LDHA), OXPHOS (COX6B1 and ATP5MC2), and nucleotide metabolism (TK1, GUK1, NME1)." (PMID 39393173, 2024).
ATP5MC2 also shares sentences with these, for which no sentence is quoted: Alzheimer disease (1 paper); infection (1).